ALK (ALK receptor tyrosine kinase)
Diseases named in the same sentence as ALK in open-access papers (continued):
Sharing a sentence is not in itself a finding about the gene and the disease.
neuroblastoma (continued). "To examine whether TNO155 could restore sensitivity in resistant ALK-F1174L neuroblastomas, we first generated a lorlatinib-resistant cell line model based on previously reported methodologies." (PMID 38032104, 2023). "The first-in-class ALK inhibitor crizotinib, limited the growth of neuroblastoma cell lines expressing amplified wild-type and R1275Q-mutated ALK, but not F1174L-mutated ALK." (PMID 37414143, 2023). "We recently demonstrated that ALK has roles in neuroblastoma cell migration and metastasis and thus, asked whether pharmacologic inhibition of ALK and/or SHP2 might impact cell migration." (PMID 38032104, 2023). "Given that ALK activation is pivotal to boost neuroblastoma growth, its degradation may slow tumor progression." (PMID 37765276, 2023). "Responses to ALK inhibitors can also be observed in diseases such as neuroblastoma, which bear ALK mutations (rather than fusions/rearrangements), but the response rates are generally only in the ~10–20% range." (PMID 37773318, 2023). "Phase I clinical trials using the second-generation ALK inhibitor ceritinib demonstrated responsiveness in a subset of patients with refractory or relapsed neuroblastoma, with indications that individuals bearing the R1275Q mutation were more sensitive to treatment." (PMID 37414143, 2023). "Although the overall frequency of ALK alterations in neuroblastoma at diagnosis has been well documented, little is known about their prevalence and prognostic impact in specific patient subgroups, still, and in patients with relapsed or progressive disease in particular." (PMID 36807339, 2023). "Moreover, ibrutinib inhibits the development of neuroblastoma xenografts in nude mice, and the combination of ibrutinib with the anaplastic lymphoma kinase (ALK) inhibitor crizotinib increases the suppression." (PMID 36903645, 2023). "Moreover, resistance to ALK inhibitors uncovered a novel oncogenic driver of neuroblastoma, Provirus Integration Site for Moloney Murine Leukemia Virus (PIM) kinase." (PMID 37414143, 2023). "ALK inhibitor activity is also seen in neuroblastoma, which bear ALK mutations (rather than fusions/rearrangements), but response rates are lower (~10–20%)." (PMID 37773318, 2023). "Furthermore, phosphoproteomics and proximitome analyses of ALK in neuroblastoma cells have revealed SHP2 as a downstream target and interactor of active ALK." (PMID 38032104, 2023). "Clinical trials of neuroblastoma ALK-mutation-positive subgroups treated with crizotinib were not successful, but new, more potent ALK TKIs are now being tested." (PMID 37892172, 2023). "ALK amplification was detected in 4.7% of neuroblastomas obtained at diagnosis (14/298)." (PMID 36807339, 2023). "Innate or adaptive resistance to ALK inhibitors often leads to short-term and/or minimal responses in ALK-aberrant neuroblastoma tumors, thus impacting their potential utility for long-term use as single agents in patients with neuroblastoma." (PMID 38032104, 2023). "Thus, understanding ALK inhibitor resistance mechanisms in neuroblastoma is of utmost clinical importance." (PMID 35689207, 2022). "Besides chromosome rearrangements, gene overexpression has been described as the relevant abnormal alterations in the ALK gene in neuroblastoma, lung, and oesophageal cancer." (PMID 36145589, 2022). "This study reports the presence of a novel de novo ALK germline F1174I mutation in an infant presenting with multifocal neuroblastoma and central hypoventilation in the absence of PHOX2B alterations." (PMID 36140661, 2022). "However, therapeutic resistance has been reported with all ALK inhibitors in neuroblastoma and other tested cancers." (PMID 36585695, 2022). "The third sample, the zPDX from the neuroblastoma culture with MYCN amplification and PIK3CA (phosphatidylinositol-4,5-bisphosphate 3-kinase catalytic subunit alpha) mutation, responded only moderately to the ALK inhibitor ceritinib out of five tested drugs." (PMID 35159116, 2022).
neuroblastoma (continued). "The mechanism by which NF1 loss abrogates ERK to RAF feedback in neuroblastoma cells harboring ALK mutations remains elusive, but this will not prevent a rapid translation of this collateral sensitivity into the clinic." (PMID 35689207, 2022). "Knockdown of p110α in neuroblastoma cells could also reduce ALK at the protein level, while overexpression of p110α upregulated ALK." (PMID 36585695, 2022). "Indeed, in neuroblastoma and in other models, ALK activation has been shown to cooperate with MYCN but also regulate MYCC expression." (PMID 36337169, 2022). "Furthermore, we found that inhibition of p110α induced ALK instability and synergized the inhibitory effects of ALK inhibitors on neuroblastoma cells." (PMID 36585695, 2022). "Sequencing of ALK mutational hotspots should be performed in neonates presenting with neuroblastoma and hypoventilation without PHOX2B mutations." (PMID 36140661, 2022). "To test whether the combination of ALK and p110α inhibitors could improve the neuroblastoma treatment, we performed cell viability assays in vitro." (PMID 36585695, 2022). "The third-generation ALK inhibitor, lorlatinib, is currently being evaluated to treat relapsed neuroblastoma in a phase I/II trial, and may soon be introduced into first-line therapy trials." (PMID 35689207, 2022). "In contrast, phase I trials with the second-generation ALK inhibitor, ceritinib, showed clinically relevant responses in a fraction of patients with refractory or relapsed neuroblastoma, but the response duration was short, indicating early resistance development." (PMID 35689207, 2022). "Moreover, altered KM, ATP values can explain primary resistance of ALK-driven neuroblastomas to crizotinib." (PMID 36357385, 2022). "Since the PI3K signaling pathway is a downstream cascade of the ALK activation, they may form a positive feedback loop in the oncogenesis of neuroblastoma." (PMID 36585695, 2022). "As ALK inhibitors are increasingly used in the treatment of refractory/relapsed neuroblastoma, our study highlights the importance of confirming whether an ALK mutation detected at diagnosis is still present in clones leading to relapse." (PMID 36029175, 2022). "Also in other tumor entities, false-positive ALK expression has been reported, e.g., in neuroblastoma mediated by MYCN amplification." (PMID 35756632, 2022). "In addition, these peptides can induce the body to generate cytotoxic T lymphocytes (CTL) specifically against ALK, which have the ability to kill tumor cells of ALK positive neuroblastoma and ALCL." (PMID 36591504, 2022). "ALK combined with N-myc (ALK F1174 C/N-myc) co-activates Wnt/β-catenin signaling, and Wnt inhibitors targeting these entities can inhibit the growth and metastasis of neuroendocrine prostate cancer and neuroblastoma." (PMID 35774359, 2022). "Here we report on a patient with multifocal, congenital neuroblastoma in association with clinical features similar to congenital central hypoventilation syndrome with a de novo germline ALK F1174I mutation in the absence of PHOX2B mutation." (PMID 36140661, 2022). "The oncogenic mechanism of ALK-A was first described in 2002 in neuroblastoma cell lines and has been discovered also in NSCLC, while point mutations of the ALK locus, most commonly in the kinase domain, have been reported mostly in patients with neuroblastoma and thyroid cancer." (PMID 36230686, 2022). "Our study identifies NF1 loss and activating RAS mutations as bona fide clinically relevant causes of ALK inhibitor resistance in ALK-driven neuroblastoma and establishes reactivation of signaling downstream from the RAS-MAPK pathway as a mechanism of ALK inhibitor resistance." (PMID 35689207, 2022). "The majority of reported ALK mutations in neuroblastoma are activating point mutations in the tyrosine kinase domain (TKD) that are present in 7–8% of all neuroblastoma cases, while amplification of the ALK locus occurs in approximately 2% of all sporadic neuroblastoma tumors." (PMID 36140661, 2022).
neuroblastoma (continued). "In order to explore de novo mutations occurring during development of ALK inhibitor resistance, we cultivated NBLW-R neuroblastoma cells (ALKF1174L, MYCN-amplified) with increasing concentrations of lorlatinib or ceritinib for a period of 3 months to generate resistant cell lines." (PMID 35689207, 2022). "Moreover, the cell lines differed with regard to the genomic status of the oncogene anaplastic lymphoma kinase (ALK), a driver of neuroblastoma growth." (PMID 35409209, 2022). "We therefore aimed to examine whether telomerase-interacting compounds in combination with established chemotherapy or ALK inhibitors act synergistically on neuroblastoma growth in vitro and in vivo." (PMID 35953764, 2022). "Moreover, ALK and MITF germline alterations were associated with neuroblastoma and melanoma risk, respectively, but this finding is intriguing for possible links with other cancers such as OC." (PMID 36555431, 2022). "Furthermore, the neuroblastoma cell line NBLW-R was rendered resistant by continuous exposure to ALK inhibitors." (PMID 35689207, 2022). "In addition, low levels of miR-96 in neuroblastoma seem to play a role in ALK overexpression, as the ALK 3′UTR has been reported to be a target of miR-96." (PMID 34771690, 2021). "Using model organisms to study ALK function poses the question of how comparable they are to human ALK and whether the findings are relevant to neuroblastoma." (PMID 34020009, 2021). "To date, ALK inhibitors such as crizotinib and entrecenib have shown efficacy in preclinical models and progressed to phase 1 and 2 trials for relapsed and refractory neuroblastoma." (PMID 34064704, 2021). "As neuroblastoma consists of mostly undifferentiated cells, a disruption of ALK activity occurring in precursors of the sympathoadrenal lineage might be triggering tumorigenesis." (PMID 34020009, 2021). "This knowledge will help us to develop better strategies for ALK-positive neuroblastoma treatment." (PMID 34769149, 2021). "The expression level of ALK in neuroblastoma cell lines was examined by qRT-PCR." (PMID 34591871, 2021). "Interestingly, several other ALK‐positive tumor patients are often younger, such as those patients with neuroblastomas, and inflammatory myofibroblastic tumors which occur most often in children and adolescents." (PMID 34596344, 2021). "Besides chromothripsis, translocation was reported as a novel mechanism of intragenic ALK rearrangements in neuroblastoma tumors in 2014." (PMID 34271921, 2021). "To date, ALK mutations and MYCN amplification are the only validated de novo drivers of neuroblastoma, although a number of other commonly over-expressed proteins and low frequency somatic mutations have been implicated in tumour progression and drug resistance." (PMID 34064704, 2021). "Therefore, studying the normal function of ALK will contribute to elucidating its role in neuroblastoma initiation." (PMID 34020009, 2021). "Subsequent tissue-specific ALK-overexpressing mouse models have been constructed that demonstrate synergy with MYCN in the ability to generate neuroblastoma and have helped to clarify the oncogenic role of ALK, but, similarly, little is known about its physiological function." (PMID 34769149, 2021). "Expression of the tyrosine kinase anaplastic lymphoma kinase (ALK) and hyperactivation of the RAS/MAPK pathway is also frequently found in high-risk and relapsing neuroblastomas, although ALK expression itself is not universally associated with a poor outcome." (PMID 33808071, 2021). "If this is the case in a neuroblastoma patient tumor setting, then some 11q deletions could potentially respond to ALK or ERK pathway inhibition, perhaps in combination with retinoic acid to promote differentiation." (PMID 34885007, 2021). "Hence, ALK has been an important therapeutic target for the development of novel drugs against aggressive neuroblastoma." (PMID 34591871, 2021).
neuroblastoma (continued). "Therefore, a novel anti-ALK drug is necessary to combat potential drug resistance to ATP-competitive TKIs in ALK-driven neuroblastoma." (PMID 34591871, 2021). "Aberrant activation of anaplastic lymphoma kinase (ALK) drives neuroblastoma (NB)." (PMID 33921066, 2021). "In 10.9% of neuroblastoma tumours with MYCN amplification, additional ALK mutations were found." (PMID 34769149, 2021). "Furthermore, these cell lines express different combinations of oncogenes known to be important for neuroblastoma development and progression, such as amplified MYCN and mutated or amplified ALK." (PMID 33889818, 2021). "More comprehensive reviews of ALK-targeted therapy in neuroblastoma are available." (PMID 34298746, 2021). "A similar resistance development event may occur in neuroblastoma patients after ALK inhibitor treatment." (PMID 34591871, 2021). "However, one report, in which ALK is driven in the mouse neural crest by either DBHiCre or TH-IRES-Cre, resulted in tumor development, highlighting the need to consider ALK expression levels carefully in a temporal and spatial context in neuroblastoma." (PMID 34885007, 2021). "They reported that expression of the ALKAL2 ligand cooperates with MYCN to drive highly penetrant and aggressive neuroblastoma growth in mice, in the absence of ALK mutation." (PMID 34885007, 2021). "Moreover, even in the absence of this deletion, a synergistic in vitro activity of the combination of an ALK inhibitor with a CDK inhibitor in neuroblastoma was reported in the literature." (PMID 33878728, 2021). "CCC-003 treatment upregulated apoptotic cell death in neuroblastoma cells and tumor tissues, suggesting that the suppression of oncogenic mutated ALK by CCC-003 was sufficient to upregulate pro-apoptotic signaling and thus exert anti-tumor effects in ALK-positive neuroblastoma." (PMID 34591871, 2021). "Interestingly, along with MYCN amplification, ALK has also been reported to be amplified in neuroblastoma." (PMID 34842635, 2021). "In addition, our understanding of the endogenous role of ALK in neural crest development is limited and inhibits us from fully understanding its involvement in neuroblastoma formation." (PMID 34769149, 2021). "PTPN1 has been linked to tyrosine dephosphorylation of the intracellular pool of ALK in mouse fibroblasts, raising the possibility that PTPN1 may dephosphorylate ALK in neuroblastoma cells." (PMID 34957126, 2021). "Many of these clinical trials have shown that ALK inhibition also sensitized tumours to standard-of-care chemotherapy, supporting the combination of ALK inhibitors with current standard-of-care treatments for the small number of patients with ALK mutant neuroblastoma." (PMID 34064704, 2021). "A more precise definition of the role of ALK during neural crest development will be crucial to our understanding of the initiation of ALK-positive neuroblastoma and will help us to develop new treatment strategies to correctly treat neuroblastoma and potentially decrease the risk of relapse." (PMID 34769149, 2021). "Future phosphor/proteomics analyses may increase our ability to identify ALK-driven neuroblastomas that may respond to ALK TKI therapy." (PMID 34885007, 2021). "This study suggests that SP141 warrants further investigation as an MDM2 antagonist, particularly in combination with other agents currently used to treat neuroblastoma, such as mTOR or ALK inhibitors, to provide improved anticancer activity against neuroblastomas with different genetic backgrounds." (PMID 33291373, 2020). "These ALK CAR-T cells can lyse ALK-positive neuroblastoma cells in co-cultures." (PMID 32059449, 2020). "ALK is involved in the initiation and progression of many cancers, including neuroblastoma." (PMID 31882403, 2020). "At present, we can only speculate on a potential role for ETV5 in trametinib resistance in ALK-activated neuroblastoma." (PMID 31937834, 2020).
neuroblastoma (continued). "Furthermore, it should be noted that the 2p24 chromosomal amplicon observed in high-risk neuroblastoma encodes other genes in addition to MYCN, such as the anaplastic lymphoma kinase (ALK)." (PMID 33585251, 2020). "To evaluate through which ALK downstream signalling axis ETV5 is regulated in neuroblastoma cells, we treated CLB-GA (ALKR1275Q), NB-1 (ALKamp), SK-N-AS (ALKwt, NRASQ61K) and SH-SY5Y (ALKF1174L) cells with inhibitors for the two major pathways downstream of ALK." (PMID 31937834, 2020). "The majority of ctDNA studies in neuroblastoma are based on digital droplet PCR or targeted sequencing that require prior characterization of the biomarkers such as MYCN amplification and activating ALK mutations." (PMID 33381456, 2020). "Truncated ALK is frequently found in neuroblastoma cancer cell lines." (PMID 32344689, 2020). "To evaluate the functional impact of ETV5 levels in neuroblastoma cells with different mutant ALK backgrounds, we performed transient (siRNA) and stable (shRNA) ETV5 knockdown in CLB-GA (ALKR1275Q), NB-1 (ALKamp), SK-N-AS (ALKwt, NRASQ61K), and SH-SY5Y (ALKF1174L) cells." (PMID 31937834, 2020). "We included in the analysis 48 cells of the CLB-BER-LUD cell line, another neuroblastoma cell line derived from a stage 4 patient with MYCN amplification but no ALK mutation." (PMID 31452835, 2019). "Alternatively, as seen in neuroblastoma, a common infant tumor that harbors ALK alterations, inherent maturation (also a part of normal development) may explain the morphological and clinical “maturation” of some iHGG into iLGG31–33." (PMID 31554817, 2019). "Indeed, these samples represented isogenic cell lines showing the same genetic alterations, including 1p loss, 17q gain and MYCN amplification, which are emblematic of neuroblastoma, and differed only by their ALK status." (PMID 31452835, 2019). "A patient with a neuroblastoma harbouring an ALK mutation (R1275Q) did not respond to TSR-011 treatment." (PMID 31217479, 2019). "The results suggest that alectinib is an effective inhibitor of ALK kinase activity in ALK addicted neuroblastoma and should be considered as a potential future therapeutic option for ALK-positive neuroblastoma patients alone or in combination with other treatments." (PMID 31334113, 2019). "Thus, treatment with repotrectinib induces an apoptotic response in ALK positive neuroblastoma cells." (PMID 31852910, 2019). "Lessons learned from the use of ALK inhibitors in adult cancers may certainly be a benefit in the setup of ALK therapy for neuroblastoma patients." (PMID 31452835, 2019). "Interestingly, inhibition of ERK5 with XMD8-92 and ALK with crizotinib has been shown to act synergistically to reduce neuroblastoma cell proliferation in vitro and human neuroblastoma xenograft growth in vivo." (PMID 30901834, 2019). "In non-hereditary cases of neuroblastoma somatic ALK mutations or amplifications have been shown to be associated with a poor prognosis, for which Crizotinib treatment is often not efficacious." (PMID 35582571, 2019). "Alectinib shows activity against RET, a downstream target of ALK in neuroblastoma, which may increase its effectiveness in this form of the disease." (PMID 35582571, 2019). "Secondly, there must be a mechanism for expression of ALK (which may be ectopically driven via a translocation partner gene promoter in the case of fusion proteins in ALCL and NSCLC, or endogenously driven in the case of mutant ALK species in neuroblastoma)." (PMID 31366041, 2019). "Furthermore, an additional mechanism of ALK activation in neuroblastoma is attributable to gene amplification, which results in increased protein expression and constitutive catalytic activity." (PMID 31366041, 2019). "The ALK tyrosine kinase receptor is oncogenically activated in neuroblastoma." (PMID 30778092, 2019).